STAT3 (signal transducer and activator of transcription 3)
Diseases named in the same sentence as STAT3 in open-access papers (continued):
Sharing a sentence is not in itself a finding about the gene and the disease.
tumor (continued). "Here, we present evidence that IL‐11 plays a major role in exacerbating tumour cell growth mediated through STAT3 and STAT1 activation." (PMID 40673604, 2025). "STAT3 is a well-known oncogenic transcription factor involved in various aspects of tumor progression, including cell proliferation, survival, and immune evasion." (PMID 41551164, 2025). "Adipocyte-derived leptin also inhibits glycolysis in CD8+ lymphocytes by activation of the enzymes involved in FAO via the STAT3 pathway, impairing their anti-tumor activity." (PMID 40227577, 2025). "All these results indicate that these compounds inhibit the STAT3 protein hindering the tumor growth and cancer progression." (PMID 40061959, 2025). "In silico analysis predicted interactions with key cancer-related targets, especially STAT3, a central regulator of tumor growth, metabolism, and cell survival." (PMID 41226114, 2025). "The current work, which is supported by the previous literature, shows that R. coriaria extract inhibits TNBC migration and invasion, suppresses angiogenesis, and lowers tumor growth in vivo via inhibiting STAT3, NF-κB pathways." (PMID 41302399, 2025). "IL-22 has been involved in mucosal defense, tissue repair, and wound healing, but also with CRC tumor progression through the activation of the STAT3 pathway, promoting cancer cell self-renewal and tumorigenesis." (PMID 41425582, 2025). "High expression of EUDAL facilitates sustained phosphorylation of EGFR in hypoxic tumor cells and subsequently activates downstream STAT3/BNIP3 signaling, which leads to autophagy-related drug resistance." (PMID 40940319, 2025). "PTPRD is inactivated in many human cancers and potentially plays a role as a tumor suppressor through STAT3 inhibition." (PMID 39985075, 2025). "The m6A‐YTHDF1 axis increases JAK1 protein translation efficiency and subsequent STAT3 phosphorylation, thus forming the METTL3/m6A/JAK1/STAT3 axis, which enhances TIMs’ immune suppressive functions and facilitates tumor immune evasion." (PMID 40443721, 2025). "Enhanced antitumor responses were also observed in parental CAL-27 and HN30 xenograft-bearing mice treated with cisplatin combined with STAT3-IN-1 (with tumor inhibition rates of 84.58%–90.38%) or CQ (with tumor inhibition rates of 80.62%–86.25%)." (PMID 40940319, 2025). "The hyperactivity of STAT3 in HCC cells has been demonstrated to enhance the malignant biological behavior of tumor cells by promoting their invasion, metastasis, and proliferation while also preventing their apoptosis." (PMID 40439888, 2025). "It has been reported that IL-6 and IL-1β can stimulate tumor cells to express CD274 (PD-L1) proteins via activating the STAT3 signaling pathway, thereby facilitating tumor cell immune escape." (PMID 39911394, 2025). "This inflammatory state activates oncogenic signaling (e.g., NF-κB, STAT3), promotes immune evasion, and provides substrates for tumor metabolic reprogramming, where cancer cells exploit lipids for growth." (PMID 41009039, 2025). "STAT3 has emerged as a promising target due to its frequent dysregulation in various malignancies, where it often acts as an oncogene, promoting tumor growth, survival, and immune evasion." (PMID 40918170, 2025). "A key mechanism of action of STAT3 is to promote the proliferation and survival of tumor cells by mimicking physiological growth-promoting signals (IL-2 and T-cell receptor (TCR) signaling pathways), thereby playing a critical role in ALCL formation." (PMID 41584605, 2025). "In these cells, activation of IL10 receptor signaling triggers STAT3 phosphorylation, which in turn promotes tumor cell survival and proliferation." (PMID 41469691, 2025). "Upon binding to the IL‐6 receptor (IL‐6R) on cell membranes, IL‐6 forms a complex with gp130 or IL‐6Rβ, triggering STAT3 activation and promoting tumor development." (PMID 40166646, 2025).
tumor (continued). "While these strategies highlight the versatility of STAT3 inhibitors, several challenges remain, including overlapping toxicities, potential resistance mechanisms, and tumor heterogeneity, which necessitate personalized treatment approaches." (PMID 40166646, 2025). "Specifically, ERα induced the expression of miR-4324 and thereby prevented tumor growth via signal transducer and activator of transcription 3 (STAT3) signaling." (PMID 40486871, 2025). "When recruited and amplified, MDSCs penetrated tumor tissue in the deep vascular deficit area and hypoxia downregulated STAT3 and expedited MDSC differentiation into TAMs." (PMID 40422244, 2025). "GDF15 promotes tumor cell proliferation and invasion by upregulating STAT3 phosphorylation or by activating ErbB2, which is central to the PI3K/AKT and mitogen-activated protein kinase (MAPK) pathways." (PMID 40868185, 2025). "Increased Proteobacteria has also been linked to oxidative stress and production of reactive oxygen species (ROS), which can induce DNA damage and activate oncogenic pathways such as PI3K/Akt and STAT3, further emphasizing tumor-promoting conditions." (PMID 41395614, 2025). "First, proinflammatory factors activate tumor pathways such as signal transducer and activator of transcription 3 (STAT3) and NF‐κB, stimulating cell proliferation and inhibiting apoptosis, which enhances tumor cell survival and growth." (PMID 41267926, 2025). "M2 TAMs secrete large amounts of IL‐10 in the TME, which stimulate JAK/STAT signaling in the tumor, lowers paclitaxel's effectiveness via the IL‐10/STAT3/Bcl‐2 cascade, and enhances paclitaxel resistance." (PMID 39927632, 2025). "In conclusion, our findings suggested that FXR exerted a tumor-suppressive effect in HCC by inhibiting the phosphorylation of STAT3 in HCC stem cells through targeting SOCS3." (PMID 39940889, 2025). "Among them, STAT1 is involved in anti-tumor immune response, while STAT3 and STAT5 exhibit pro-tumorigenic properties, and their overexpression is closely associated with tumor progression and malignancy." (PMID 40364836, 2025). "STAT3 has been reported to control the ability of pre-neoplastic and malignant cells to resist apoptosis-based tumor-surveillance, regulate tumor angiogenesis, and promote invasiveness." (PMID 40444012, 2025). "Nuclear PKM2 acts as a protein kinase and promotes tumor growth via the activation of oncogenic pathways such as STAT3." (PMID 41425711, 2025). "IL‐6, secreted by primary tumor cells and associated stromal cells, promotes PMN formation by activating STAT3 in tumor cells and tumor‐infiltrating myeloid cells." (PMID 40470380, 2025). "They demonstrated that the E3 ubiquitin ligase COP1 interacts with STAT3, mediating its ubiquitination and degradation, while miR-424 promotes STAT3 stabilization and activity, thereby facilitating tumor progression by targeting COP1." (PMID 40771930, 2025). "Targeting STAT3 with specific inhibitors can suppress the expression of pro-inflammatory cytokines and chemokines, potentially reducing tumor growth and enhancing the efficacy of ICIs in HNCs." (PMID 41463272, 2025). "Constitutive STAT3 activation in tumor cells is a well-established driver of immunosuppression, promoting IL-10 production and Th2/M2 skewing in the microenvironment." (PMID 41403933, 2025). "As is known, IL-6 functions as the activator of the canonical STAT3 pathway mediating cancer cell proliferation and metastasis as well as the suppressor of tumor immune responses." (PMID 40158127, 2025). "To mechanistically assess the role of neutrophil-STAT3 in tumor growth and progression, we generated a mouse strain carrying neutrophil-specific knockout (NStat3−/−) by utilizing a Ly6G-Cre system, which has a high degree of specificity for neutrophils." (PMID 40885734, 2025). "Beyond checkpoint regulation, STAT3 profoundly alters T cell dynamics within the tumor microenvironment (TME)." (PMID 40704145, 2025).
tumor (continued). "Immunofluorescence analysis further indicated that M@CuB-Lips markedly downregulated the levels of p-STAT3 protein at the tumor site within the brain." (PMID 41145734, 2025). "IL-6, in particular, is a powerful driver of Signal Transducer and Activator of Transcription 3 (STAT3) activation in both immune and tumor cells, supporting chronic inflammation, resistance to cell death, and the preservation of cancer stem cell traits." (PMID 40940809, 2025). "LIF secreted by iCAFs subsequently activates the STAT3 signaling pathway in cancer cells, which promotes tumor progression." (PMID 40136652, 2025). "Tumor-associated neutrophils (TANs) have been shown to produce interleukin IL-17a, which promotes epithelial–mesenchymal transition of GC cells via JAK2/STAT3 signaling." (PMID 40136652, 2025). "Given the complexity of STAT3’s biological roles and its diverse effects depending on tumor type and disease stage, future therapeutic strategies should adopt a personalized medicine approach." (PMID 40704145, 2025). "Mechanistically, NEAT1 acts as a molecular reservoir for several tumor suppressor miRNAs such as miR-449b-5p, which de-activate key oncogenic targets such as c-Met and STAT3, which are key players in cell proliferation, invasion, and apoptosis." (PMID 40896358, 2025). "This study elucidated the mechanism by which sVASN enhanced the nuclear translocation of p-STAT3 (Tyr705), which further initiates cascades of gene expression in different types of cells to accelerate tumor malignant progression." (PMID 40430053, 2025). "Since constitutive STAT3 activation is a well-established driver of tumor progression in various cancers, these findings position NRN1 as a potential upstream regulator of this oncogenic pathway." (PMID 41425077, 2025). "Iron chelation and FPN induction have been shown to reduce IL6 mRNA and deactivate the STAT3 pathway, lowering intracellular iron levels and inhibiting OC tumor cell proliferation and metastasis." (PMID 40427188, 2025). "Functional interactions between the WNT and STAT3 pathways in tumor initiation and metastasis have been reported." (PMID 40952540, 2025). "Several studies have shown that the activation of STAT3 in tumor cells attenuates tumor surveillance by NK cells through cytokine secretion." (PMID 40430040, 2025). "Activated p38 MAPK/STAT3 signaling is required for the induction of autophagy 44-46, which enhances the proliferation and survival of tumor cells by supplying nutrients." (PMID 41281755, 2025). "The abnormal activation of STAT3 contributes to an immunosuppressive tumor microenvironment in GBM, leading to inadequate infiltration of cytotoxic immune cells." (PMID 41145734, 2025). "Chronic inflammation within the PDAC microenvironment is associated with genetic instability, increased mutation rates, and the activation of oncogenic pathways, such as the NF-κB and STAT3 pathways, further accelerating tumor progression." (PMID 39869563, 2025). "SOCS3 plays a crucial role in the anti-tumor effects of the pathway by promoting cell apoptosis through inhibition of STAT3 phosphorylation and subsequent downstream factors." (PMID 40426998, 2025). "In DCs, the activation of the IRF3/IFN-I signaling cascade promotes antitumor activity, whereas the NF-κB/IL-6/STAT3 axis activation escalates tumor progression." (PMID 41176596, 2025). "STAT3 is one of the key molecules regulating the expansion and activation of tumor MDSCs and can modulate the immunosuppressive activity of MDSCs through multiple mechanisms (." (PMID 40069590, 2025). "Alleviation of these effects by systemic depletion of CD8+ T cells further supports the critical role of p-STAT3/HLF/TFEB transactivation–regulated PD-L1 expression in tumor immunogenicity." (PMID 40779629, 2025). "The antitumor or pro-tumor role of IL-10 is linked to the phosphorylation of signal transducer and activator of transcription (STAT) 1 or STAT3." (PMID 41041322, 2025).
tumor (continued). "For example, pro-inflammatory cytokines in the tumor microenvironment (e.g., IL-6, TNF-α, and IL-1β) can activate signaling pathways (e.g., NF-κB and STAT3) that promote tumor cell proliferation, invasive capacity, and resistance to therapy." (PMID 39940440, 2025). "CircKIF4A, which is overexpressed in TNBC, indirectly enhances angiogenesis through the activation of the STAT3 pathway, which upregulates key vascular endothelial growth factors and cytokines, enabling rapid tumor progression." (PMID 40740236, 2025). "Synchronously, hypoxia-inducible factor 1α (HIF-1α), which is elevated in tumor-bearing conditions, collaborates with STAT3 to shift muscle metabolism from oxidative phosphorylation to glycolysis." (PMID 40704145, 2025). "Scientific studies have indicated that STAT3 remains persistently activated in various cancers and plays a crucial role in tumor initiation and progression." (PMID 40166646, 2025). "Equally, Hsp90 inhibition has been linked to the downregulation of STAT3 and TWIST1 transcription pathways, thereby inhibiting tumor progression, metastasis, and chemoresistance in diverse tumors." (PMID 39936995, 2025). "Metformin has also been reported to down-regulate PD-L1 on tumor cells via the IL-6/JAK2/STAT3 pathway." (PMID 41374963, 2025). "Specifically, within this family, STAT1 and STAT3 were identified as crucial regulators in the control of PD-L1 expression on tumor cells." (PMID 39809736, 2025). "Tumor-derived factors such as IL-6 and GM-CSF induce Stat3 activation, which maintains MDSC immaturity through sustained expression of S100A8/A9 proteins and prevents differentiation." (PMID 41584838, 2025). "These STAT3 + reactive astrocytes generate cytokines and other substances that impede the body's appropriate response to the tumor, thereby compromising both the innate and adaptive immune systems." (PMID 39780275, 2025). "MCPIP1 is a key regulator of PC progression, acting as a tumor suppressor by inhibiting the IL6/JAK/STAT3 signaling pathway." (PMID 40874680, 2025). "The mRNA expression levels of STAT3 in the tumor tissues of the RRTS-H and RRTS-M groups were significantly reduced (P < 0.01), and the expression levels in the RRTS-L group were notably reduced (P < 0.05)." (PMID 40351419, 2025). "Our results indicate that hypoxia-induced EGFR phosphorylation does not trigger Akt or ERK activation but instead leads to the activation of STAT3, which in turn induces autophagy in tumor cells." (PMID 40940319, 2025). "For example, low levels of IL-6 are beneficial for neuronal survival, while elevated or prolonged IL-6 exposure can promote tumor growth by activating STAT3 signaling." (PMID 40843259, 2025). "Tumor cells can also activate the signal transducer and activator of transcription 3 (STAT3) signaling pathway to suppress NK cell activity." (PMID 40507294, 2025). "Enhanced STAT3 activity plays a critical role in tumor development, affecting both tumor and immune cells." (PMID 40358184, 2025). "STAT3 plays a key role in pro-tumor machinery across many cell types of the tumor immune microenvironment (TIME)." (PMID 40356899, 2025). "Preclinical studies in TNBC models showed that Tocilizumab reduced STAT3 activation by 50%, resulting in decreased tumor cell proliferation and metastasis." (PMID 41463071, 2025). "To verify STAT3 activity in neutrophils at the protein level, we evaluated tyrosine-phosphorylated STAT3 (pSTAT3) levels in neutrophils from the tumor tissue and blood of HNC patients via flow cytometry." (PMID 40885734, 2025). "This study highlights the efficacy of NLP-EXOSOME COMPLEX STAT3 silencer treatment in inhibiting STAT3 expression, reducing tumor proliferation and prolonging survival in GBM models." (PMID 40427146, 2025). "Complex 1 dramaticallyreduced the phosphorylation of STAT3 in xenografted tumor tissueswith negligible influences on JAK2 phosphorylation." (PMID 41152016, 2025).
tumor (continued). "STAT3 plays a significant role in shaping the immunosuppressive tumor microenvironment (TME), contributing to immune evasion by upregulating immune-suppressive cytokines (e.g., IL-10, TGF-β) and downregulating pro-inflammatory cytokines." (PMID 40075607, 2025). "To counteract this pathway, we utilized a cell-penetrating peptide specific to ENSA-K63 lactylation, effectively blocking K63 lactylation and consequently inhibiting STAT3 activation in both tumor cells and macrophages." (PMID 39883522, 2025). "WP1066 downregulated the level of PD‐L1 through the inhibition of STAT3, which further inhibited the binding of PD‐L1 and PD‐1, thereby providing effective tumor immunotherapy." (PMID 40364727, 2025). "Epithelial ovarian cancer cell–derived EVs contain miR-222-3p, which regulates the SOCS3/STAT3 pathway and induces macrophage polarization to the tumor-promoting M2 phenotype." (PMID 40574844, 2025). "BFT additionally activates the STAT3 regulatory Th17 cells, which produce IL-17 and promote tumor development." (PMID 40520902, 2025). "Our research revealed that MSGA activated JAK1/3-STAT1 and downregulated STAT3 phosphorylation to reprogram macrophages into an anti-tumor M1 phenotype." (PMID 40786029, 2025). "High expression of CCL20 not only promotes the appearance of EMT in HCC cells, but also activates STAT3 to induce Th9 helper T cells with tumor‐promoting effects targeting the HCC tumor microenvironment." (PMID 40145607, 2025). "These reprogrammed astrocytes secrete IL-6 and IL-1β, activating JAK2/STAT3 signaling in tumor cells and enabling dynamic switching between dormancy and proliferation within the CNS niche." (PMID 41562063, 2025). "Collectively, these results show that targeting STAT3 signaling specifically in neutrophils significantly impairs tumor progression in mice." (PMID 40885734, 2025). "Forthermore, Western blot and IHC analysis confirmed that SJZD had downregulated STAT3 protein expression in tumor tissues." (PMID 41280323, 2025). "In this context, IL-6 trans-signaling stimulates tumor cell proliferation and inhibits apoptosis through activation of gp130, JAKs, and STAT3 in tumor cells." (PMID 40944094, 2025). "A recent study found that, in mice model, a high fat diet elevated IL-6 secretion by prostate macrophages, which triggered STAT3-driven growth of myeloid-derived suppressor cells and fostered a tumor-promoting." (PMID 39891849, 2025). "For example, tumor and stromal cells promote inflammation and immunosuppression through NF-κB and STAT3, which promotes tumor cells to evade immune recognition and participate in tumor cell proliferation, metastasis, drug resistance, and tumor angiogenesis." (PMID 40420185, 2025). "Signal transducer and activator of transcription 3 (STAT3) is a transcription factor that is constitutively activated in cancer cells and functions as an oncogene essential for carcinogenesis and tumour development." (PMID 40407951, 2025). "Recent studies have highlighted STAT3 as a key regulator of ferroptosis in gastric cancer, where it inhibits tumor growth and mitigates chemotherapy resistance." (PMID 40165005, 2025). "Despite promising findings, resistance to BET-targeted therapies have been observed, particularly in TNBC, where TAMs sustain tumor growth through IL-6/IL-10–driven STAT3/NF-κB signaling." (PMID 41583469, 2025). "utilized the fat‐mass and obesity‐associated protein (FTO) to epigenetically inhibit APOE expression in PTC, leading to the inhibition of glycolytic metabolism via the IL‐T/JAK/STAT3 signalling pathway and subsequent suppression of tumour growth." (PMID 39810624, 2025). "Numerous studies have shown constitutive activation of STATs, in particular STAT3, in a variety of human tumor cell lines and malignancies." (PMID 40217305, 2025). "In most samples, STAT3 protein expression was detected both in the tumor compartment (56%, n = 31) and in the immune microenvironment (69%, n = 38)." (PMID 40426911, 2025).